YWHAZP1 (tyrosine 3-monooxygenase/tryptophan 5-monooxygenase activation protein zeta pseudogene 1)
Synonyms: formerly YWHAZP
Gene: Processed pseudogene on chromosome 14 (44,290,997 to 44,291,718, reverse strand). Ensembl gene ENSG00000259148.
Diseases named in the same sentence as YWHAZP1 in open-access papers:
YWHAZP1 is named in the same sentence as 1 disease in open-access papers, as found by Europe PMC text mining. Sharing a sentence is not in itself a finding about the gene and the disease. The quoted sentences say what the papers report.
psoriatic arthritis (1 paper, 2024). Joint inflammation associated with psoriasis. "A study of T cells from the blood and synovial fluid of psoriatic arthritis patients revealed the expression of YWHAZP3 and YWHAZP10 in both leukocytes and T cells; the expression of YWHAZP1, YWHAZP5, and YWHAZP6 in leukocytes only; the expression of YWHAZP2 in T Cells only." (PMID 38674334, 2024).